IL21 (interleukin 21)
Diseases named in the same sentence as IL21 in open-access papers (continued):
Sharing a sentence is not in itself a finding about the gene and the disease.
infection (continued). "Taken together, these data indicate that IL-21 signaling plays multiple roles during establishment of MHV68 infection, and identify IL-21 as a critical TFH cell-derived factor for efficient establishment of gammaherpesvirus B cell latency." (PMID 25875847, 2015). "This suggests either that other subsets of CD4+ T cells can produce IL-21, or that Th1/Th2/Th17 subsets activated in infections can acquire an additional Tfh phenotype." (PMID 25763578, 2015). "Similar to infection, we observed a robust expression of the Th17-related genes RORγt, IL-23p19, IL-17F, IL-21 and IL-22." (PMID 26490738, 2015). "Future similar prospective studies in patients detailing how pre-infection levels of IL-21-producing cells correlate with the outcome of HIV-1 exposure would be valuable in fully understanding the prognostic significance of IL-21 during HIV-1 disease." (PMID 26108174, 2015). "During the memory phase, we found that IFN-γ+ T cells at day 60 post-infection were able to produce IL-21." (PMID 26646149, 2015). "Th17 cells produce well-known soluble molecules such as IL17A, IL17F and IL21 which are important for neutrophil recruitment, infection clearance and delivery of antimicrobial peptides." (PMID 25495206, 2014). "Our unpublished data suggested that there is minimal IL–21 release or expression into the IAV infected lungs before day 5–6 post infection." (PMID 25251568, 2014). "A representative co-staining of IL-17 and IFN-γ within intestinal CD4+ T cells is shown in one IL-21-treated and one control RM at wks-2 (pre-infection), 4 (during the IL-21 treatment) and 23 p.i.." (PMID 23853592, 2013). "An up-regulation of Ccl3, Ccl4, Ccl5, and Tgfb, a strong CD4+ T-cell response, and down-regulation of Il17, Il21 and Il23 occurred during infection." (PMID 23383148, 2013). "While we have previously shown that IL-17–producing CD4+ T (Th17) cells were barely detectable in LCMV-DOC infection, it remains possible that IL-21 inhibits Treg cell expansion by regulation of IL-6." (PMID 23696736, 2013). "Conversely, IL-21 producing CD4+ T cells are lost very early in infection though other cellular subsets such as CD8 T cells have been shown to upregulate IL-21 production." (PMID 23762098, 2013). "Given that CD4+ and CD8+ T cells are a source of IL-21, expression of this cytokine by these populations in the spleen and brain was examined after infection." (PMID 23667536, 2013). "Together with the Treg cell-intrinsic negative IL-21R−/− signaling observed in WT:IL-21R−/− mixed BM chimeras, these data suggest that IL-21 restricted the virus-driven Treg cell expansion in LCMV-DOC infection independently of IL-6 signaling." (PMID 23696736, 2013). "The increased expression of IL-21R in the vagina after HSV-2 infection supports that IL-21 is induced at the innate stages of infection." (PMID 24358128, 2013). "Perforin and GrB analysis was performed at wks-2 (pre-infection), 2 (pre-IL-21 administration), 4 and 6 (during IL-21 treatment), 10 and 23 p.i. in PBMC; at wks-2, 2, 4, 6 and 23 in RB and at wks-2, 2, 6 and 23 in LN." (PMID 23853592, 2013). "At numerous experimental points pre- and post-infection, as well as pre- and post-IL-21 treatment, peripheral blood (PB), rectal biopsies (RB), and lymph nodes (LN) were collected from all 12 RMs." (PMID 23853592, 2013). "Consistent with an effect of IL-21 on Th17 cells, plasma levels of IL-22 were higher in IL-21-treated than control animals at wk6 post infection (fold change wk6 vs. wk2: 5.6±1.82 vs. 1.02±0.39; P = 0.056)." (PMID 23853592, 2013). "To analyze the magnitude of the effects of IL-21 treatment on sCD14 and LPS levels, we then compared the levels of these two markers at baseline (before infection) versus at wk23 post-infection." (PMID 23853592, 2013). "IL-21 also provides a critical signal for the differentiation of B cells into plasma cells and for protection against secondary challenge infection with H. polygyrus." (PMID 23053394, 2012).
infection (continued). "Serum levels of IL-21 are significantly reduced in HIV-infected individuals early in infection and positively correlated with CD4+ T cell counts." (PMID 22511950, 2012). "It has been recently shown that IL-21 production is increased during chronic viral infections and is essential in containing the infection via its action on CD8+ T cells." (PMID 23064011, 2012). "After systemic infection with L. donovani, a relatively silent phase during the first ∼3 weeks of infection was followed by increased expression of IL-4, IL-10, IL-13, and IL-21." (PMID 22275864, 2012). "The low correlations were influenced by Asp infection (lime green star) showing distinctly higher levels for IL‐21 and IL‐22 compared to other types of infection, and MRSA infection (red square) showing distinctly higher levels of TNFα as compared to other infection types." (PMID 40031928, 2025). "What’s more, the cytokines IFNγ and IL-21 were both strongly induced, which could indicate that infection stimulates double producers or that follicular helper T (TFH) cells were also released from the spleen." (PMID 40214640, 2025). "In addition, E2-specific memory B cells (MBCs) from individuals who spontaneously resolved HCV infection were observed to peak early after infection (4–6 months), correlating with the expansion of activated cTfh cells expressing interleukin 21 (IL-21)." (PMID 39205311, 2024). "In addition, the IL-21-expressing CD3γ/δ T cells were detected in tissues and markedly increased in the anterior, middle and posterior intestine after infection with A. hydrophila." (PMID 37759501, 2023). "At 3 h post infection the IL-21 level was 60% which decreased significantly at 6 h (30%, p < 0.0001), 12 h (27%, p < 0.0001) and finally decreased to the level 20% (p < 0.0001) at 24 h post infection when compared to the level expressed at 0 h post JEV infection." (PMID 36707891, 2023). "Moreover, upregulation of RORγt, IL-21 and IL-22 indicates a pronounced Th17 immune response following infection in vaccinated mice." (PMID 36918600, 2023). "We found that il21 expression was induced in the primary head kidney leukocytes of grass carp (Ctenopharyngodon idella) by heat-inactivated Aeromonas hydrophila (A. hydrophila) and LPS and in tissues after infection with A. hydrophila." (PMID 37759501, 2023). "In the gills, il21 was significantly upregulated after infection at 24, 48 and 72 h." (PMID 37759501, 2023). "Levels of 3 mediators, CXCL11, CCL19, and IL-21, were higher in patients whose symptoms resolved after antibiotic therapy, implying that they might play a protective role in the infection and contribute to symptom resolution." (PMID 37209716, 2023). "This study aims to investigate whether IL-21 is produced in T cells and, if so, whether the IL-21 producing T cells can be modulated after infection with bacterial pathogens." (PMID 37759501, 2023). "The level of IL-21 was decreased with increasing time points post infection." (PMID 36707891, 2023). "In summary, we have shown that grass carp il21 was induced during infection with A. hydrophila." (PMID 37759501, 2023). "Il21 was induced in the anterior intestine at 24, 48 and 72 h post-infection." (PMID 37759501, 2023). "In the present study, we only detected low titer antibody responses in the bats, even at 21 days post infection, and the reduction of IL-21 expression may be one reason why antibody titers, which are principally a function of affinity maturation, are poor." (PMID 37856551, 2023). "In addition, documented to recruitment neutrophil during inflammation, S100A8 mRNA expression was reduced in lungs of IL-21R−/− mice after infection, which also partly accounted for lower neutrophil chemotaxis when IL-21/IL-21R blocked." (PMID 35693111, 2022). "In addition, at week 3 post infection the expression level of the il21 gene was lower in B-IL-6KO mice." (PMID 35154093, 2022).
infection (continued). "Upon expansion, IL-21, one of the major Tfh cell-derived cytokines, has been shown to be important in the development of robust and durable class-switched B cell responses following blood stage infection with P. chabaudi AS and P. yoelii XNL." (PMID 36146602, 2022). "Indeed, modulation of IL-21 receptor expression by KSHV infection is one possible mechanism for the synergistic promotion of plasma cell numbers we observe with both IL-21 treatment and infection." (PMID 36569889, 2022). "In addition, at the early stage of infection lung cells of B-IL-6KO mice expressed significantly less il21 mRNA." (PMID 35154093, 2022). "The response of intracellular IFN-γ, IL-17A, and IL-21 expressing CD4+ or CD8+ effector T cells in HBV resolved infection was significantly higher than observed in OBI or CHB (P < 0.05), while the concentration of circulating IL-17A was higher in OBI and CHB (P < 0.01)." (PMID 35464946, 2022). "Based on broad effects on target cells, IL-21/IL-21R was demonstrated to have pleiotropic effects on humoral and cellular immunity as well as additional inflammatory pathways, implying its regulatory properties in infection, autoimmunity, and cancer." (PMID 35693111, 2022). "As Plasmodium-infected humans are likely to have been previously exposed and have received interventional treatment for previous infections that blunt GC reactions, it will be important to address if IL-21 influences the formation of memory populations when concentrations are preemptively moderated." (PMID 35631044, 2022). "We then repeated these supplementation experiments with only the 100pg/ml dose of recombinant IL-21 in an additional 12 tonsil specimens and examined both overall infection and subset-specific responses in these cultures at 3 dpi using our established B cell immunophenotyping panel." (PMID 36569889, 2022). "However, we observed a trend of increased infection in response to IL-21 treatment, and the effect seems to be stronger in the more susceptible samples." (PMID 36569889, 2022). "Higher levels of IL-15 and IL-21 in the local environment during SIVagm infection as compared to SIVmac infection might allow NK cell terminal differentiation." (PMID 33627642, 2021). "Interestingly, it was observed that IL-21, which plays a critical role in regulatory B cell differentiation, was significantly increased in B220+/IL-21+ in in vivo infections." (PMID 35071041, 2021). "This may provide a potential explanation for the lessened antiviral capacity during LCMV Cl 13 infection; even though, the reduced IL-21 production is eventually able to promote viral clearance." (PMID 34696381, 2021). "Upregulation of IL21 and IL17A was strongly associated with infection and female sex, suggesting the involvement of Th17 cells in the antichlamydial immune response and that Th17 cell responses might be heightened in females relative to those in males." (PMID 31964744, 2020). "We found that an intact IL-21/IL-21R axis was required for resistance against and clearance of enteric infection with this pathogen and that activated CD4+ T cells were the exclusive expressors of IL-21 following infection with C. rodentium in the distal colon." (PMID 30818341, 2019). "In contrast to potential roles played by the IL-21/IL-21R signaling axis in protective immunity during infection with trematodes, earlier studies demonstrated that the IL-21/IL-21R signaling pathway promotes the induction of tissue damage following Schistosoma spp." (PMID 31867283, 2019). "IgD-CD138+ plasma B cells and IL-21 production were markedly enhanced after PR8 infection." (PMID 31744227, 2019). "Interestingly, sCD40L and IL-21 were significantly downregulated in obese mouse serum prior to infection." (PMID 30046592, 2018).
infection (continued). "Concurrently, Bcl-6 protein level was remarkably lower in Uba3-deficient CD4+ T cells than in Uba3-sufficient counterparts at day 7 of infection, and the proportion of IL-21-producing CD4+ T cells in the spleen was also found to be lower in Uba3ΔT mice at this time." (PMID 30462731, 2018). "In a chronic infection, IL-21 production by Tfh cells has been shown to be the primary mechanism by which CD4 T cells help maintain CD8 T cell effector functions at late stages of infection." (PMID 28715493, 2017). "Levels of numerous cytokines, including IL-21, may be influenced by length of illness in other infections." (PMID 28427414, 2017). "In addition, we delineate a hierarchical requirement of signals previously associated with T-B cell interactions in the control of this infection, following the order IL-21 > Tfh cells > SAP." (PMID 28888925, 2017). "However, it is worth noting that Tfh-type cytokines IL-21 was elevated at 4 weeks post-infection and reached a plateau from week 7 to week 12 post-infection before decreasing gradually." (PMID 29192177, 2017). "However, important questions remain including the timing of the production of IL-6, IL-21 and IL-27 during Tfh differentiation and the GC reaction in different contexts of infection and immunisation." (PMID 31557986, 2016). "The upregulated expression of IL-21 might imply an enhanced function of Tfh cells in acute phase infection." (PMID 27266984, 2016). "We used MBMC mice to determine whether IL-21 signaling is required for T cell expansion during infection, a strategy that facilitates the direct comparison of WT and IL-21R−/− T cells in the same inflammatory environment in vivo." (PMID 27819295, 2016). "However, the numbers of B220+CD138high plasmablasts in BM from Il21-/- and Il21r-/- mice, and the numbers of B220–CD138high plasma cells in BM from Il21-/- mice were reduced at day 32 post-infection compared to those of WT C57BL/6 controls." (PMID 25763578, 2015). "We also tested the activity of IL-21 against infection with primary HIV-1 isolates." (PMID 26108174, 2015). "In line with the absence of IgG antibodies, there was also a loss of both P. chabaudi-specific IgG antibody-secreting-cells (ASC) in the BM, and of P. chabaudi-specific IgG MBC in the spleen at day 32 post-infection in both Il21-/- and Il21r-/- mice when compared with WT C57BL/6 controls." (PMID 25763578, 2015). "Finally, we demonstrate that this IL-21-STAT3-dependent IL-1β expression can at least in part explain the pathologic immune response mediated by IL-21 during infection with Pneumonia Virus of Mice (PVM), a mouse model for human respiratory syncytial virus." (PMID 26269257, 2015). "Because of this, we hypothesized that IL-21 plays a major role in promoting establishment of MHV68 infection." (PMID 25875847, 2015). "Thus, the requirement for IL-21 to activate Tfh responses seems to be highly dependent on the model of immunization or infection studied." (PMID 25763578, 2015). "Indeed, at later stage of infection IL–21 was present in the lung mostly derived from IAV-specific CD4+ T cells entering the infected lungs from the dLN." (PMID 25251568, 2014). "Therefore, to elucidate the function of IL-21 in antibody production, CD8+ T cell responses, and regulation of the immune response after infection, Il-21−/− mice were challenged with T. gondii." (PMID 23667536, 2013). "Furthermore, as the infection progressed the number of total cells recovered from the brain of Il21−/− mice continued to decline compared to their wild-type littermates (data not shown)." (PMID 23667536, 2013). "To test this hypothesis, in this study we infected twelve RMs with SIVmac239 and at day 14 post-infection (p.i.)treated six of them with rhesus rIL-21-IgFc (IL-21 throughout the manuscript)." (PMID 23853592, 2013).
infection (continued). "To test this hypothesis, we used the nonhuman primate model of SIV infection in rhesus macaques (RMs) and treated the animals with IL-21 during the acute phase of infection (i.e., starting at day 14)." (PMID 23853592, 2013). "However, when Il21−/− mice were orally infected with ME49 cysts mice survived acute infection, but succumbed to chronic infection between 50-60 days post-infection." (PMID 23667536, 2013). "Furthermore, while the number of PNA+ B cells in the spleen increased in wild-type mice over the course of the infection Il-21−/− mice showed only a marginal gain." (PMID 23667536, 2013). "One possible explanation for the different outcomes using Il21r−/− and Il21−/− mice may be the route of infection used, as oral infection may have had an affect on dissemination of the parasite as well as priming of the acute response." (PMID 23667536, 2013). "Future research in this area could focus on unravelling how IL-21 affects epithelial cells during infections and." (PMID 24358128, 2013). "Here, we treated SIV-infected rhesus macaques with IL-21-IgFc in the early stage of infection." (PMID 23853592, 2013). "The IL-21R was expressed by the vaginal epithelia and the increase in IL-21R expression was due to increased receptor expression in the vaginal epithelial cells, suggesting a role for IL-21 signalling through the IL-21R at this early and innate stage of infection." (PMID 24358128, 2013). "It is tempting to speculate that IL-21 might aggravate immunopathology by suppression of Treg cells in this infection model." (PMID 23696736, 2013). "Recent studies suggest that increased production of IL-21 may be detrimental in fighting certain infections." (PMID 23064011, 2012). "In particular, IL-21 stimulates B cell proliferation, promotes B cell maturation and IgG production including the generation of long-lived and high affinity plasma cells and memory cells that are crucial for long-term protection against infections." (PMID 23064011, 2012). "IL-4 expression continued to increase over time (from 2.3 to 4.4 fold) for the wild-type strain but remained unchanged for the avirulent mutant while IL-21 transcript showed a significant increase (4.0 fold) only at 8 hours post infection with the virulent strain." (PMID 22675469, 2012). "IL-21 plays key roles by stimulating multiple cell types across a range of infections." (PMID 23053394, 2012). "Because both IL-21 and anti-α4β7 therapy individually affect intestinal mucosal immune response, we next performed 16S rRNA gene sequencing on longitudinal fecal samples to characterize changes in microbial communities during both infection and therapeutic intervention." (PMID 39903521, 2025). "It is envisaged that these IL-21-producing CD3γ/δ+ T cells could play important roles in the maintenance of immune homeostasis in fish and the control of excessive inflammation during infections." (PMID 37759501, 2023). "At 3 h post infection the IL-21 level was 95% which decreased significantly at 6 h (74%, p < 0.0038), 12 h (55%, p < 0.0005) and finally decreased to the level 37% (p < 0.0001) at 24 h post infection when compared to the level expressed at 0 h post JEV infection." (PMID 36707891, 2023). "We discovered different mRNA expression level of NF-κB p65 subunit in two groups of mice after infection, suggesting this signaling pathway could represent as potential target for IL-21/IL-21R regulation on neutrophil response during C. muridarum infection, while its role is to be tested further." (PMID 35693111, 2022). "To determine whether the increase in total plasma cell frequency and/or increased infection of plasma cells was directly correlated with the effect of IL-21 on total KSHV infection, we performed linear model regressions and analyzed the results using Pearson’s method." (PMID 36569889, 2022).